ERBB2 (erb-b2 receptor tyrosine kinase 2)
Diseases named in the same sentence as ERBB2 in open-access papers (continued):
Sharing a sentence is not in itself a finding about the gene and the disease.
breast cancer (continued). "Although ERBB2-targeted therapies, such as lapatinib, revolutionized management of ERBB2-overexpressing breast cancer, primary and acquired resistance remains a major obstacle for the cure of this deadly disease." (PMID 29799521, 2018). "The samples represented four main mRNA-defined PAM50 breast cancer subtypes, namely basal-like, luminal A, luminal B, and ERBB2-positive subtypes." (PMID 29503809, 2018). "The incidence of breast cancer-related mortality is high, especially in ErbB2-positive patients, and acquired resistance to ErbB2-targeted anti-cancer drugs constitutes a major setback for treatment." (PMID 29352243, 2018). "A study from 2010 revealed a significant association between Beclin1 deletion and human epidermal growth factor receptor 2 (ErbB2) amplification, thus providing evidence for decreased Beclin1 expression in a particular breast cancer subtype." (PMID 29643976, 2018). "In conclusion, our data demonstrate that ganetespib is a potent therapeutic agent for ErbB2+ breast cancer cells." (PMID 29717218, 2018). "In ErbB2-positive breast cancer cells, NF-κB was found to upregulate GLS1, thus acting as an oncogenic signal promoting Gln utilization." (PMID 29666362, 2018). "We have now identified a novel mechanism of ErbB2-dependent inhibition of breast cancer cell anoikis." (PMID 30545388, 2018). "Together, these data indicate that ErbB2+ breast cancer cells are sensitive to the anti-proliferative actions of ganetespib." (PMID 29717218, 2018). "Although ErbB2-targeted therapeutics have significantly improved ErbB2+ breast cancer patient outcomes, therapeutic resistance remains a significant challenge." (PMID 29717218, 2018). "Our results showed that, in addition to cell cycle arrest, ganetespib also induces significant apoptosis in ErbB2+ breast cancer cells, as indicated by the Annexin V/PI assay and PARP cleavage." (PMID 29717218, 2018). "The development and clinical application of ErbB2-targeted therapeutics, such as trastuzumab and lapatinib, have significantly improved clinical outcomes in patients with ErbB2-positive (ErbB2+) breast cancer." (PMID 29717218, 2018). "Human epidermal growth factor receptor 2 (Her2, ERBB2) is overexpressed in about 25% of sporadic human breast cancer cases, which correlates with poor prognosis." (PMID 29799521, 2018). "In order to gain detailed insight into ganetespib-mediated growth inhibition, particularly in ErbB2+ breast cancer cells, we treated BT474 and SKBR3 cells with ganetespib (250 nM) for 24 hours, followed by cell cycle analysis using flow cytometry." (PMID 29717218, 2018). "A pertinent work showed the suppressive effects of PPARγ antagonism in populations of cancer stem cells (CSCs) derived from ERBB2-positive breast cancer cell lines (BT474 and SKRB3)." (PMID 29966227, 2018). "In the current study, we explored the structure and function of breast cancer feed arteries from mice with ErbB2-induced breast cancer." (PMID 29566737, 2018). "Regarding de novo fatty acid synthesis, in ERBB2 (erythroblastic oncogene B)-positive breast cancer cells, a remarkable amount of lipid droplets was observed." (PMID 29966227, 2018). "The RTK family includes a number of growth factor-mediated receptors, such as IGF1R, EGFR, and ErbB2/Her2, that are reported to promote several hallmarks of breast cancer." (PMID 30214383, 2018). "We, thus, propose GroA as a promising candidate for breast cancer treatment, and pinpoint the ErbB2–nucleolin interaction as a novel target for further development of anti-cancer therapeutics." (PMID 29352243, 2018). "Tumor 0903 exhibited 15% (19/127) and Tumor 0909 exhibited 40% (36/90) of the total HER2-positive breast cancer cells as expressing the t-erbB2 protein forms." (PMID 29872719, 2018).
breast cancer (continued). "Molecular analysis of RTK signaling in BT474 and SKBR3 ErbB2+ breast cancer cells indicated that the combination of lapatinib with low-dose ganetespib (50 nM) enhances the inhibition of ErbB2, Akt, Erk1/2, mTOR, and GSK3 activation/phosphorylation." (PMID 29717218, 2018). "For example, hormonal therapies such as Tamoxifen have efficacy in breast cancers expressing the oestrogen receptor (ER) while cancers with ERBB2 amplification (HER2) can be treated with HER2 targeting therapies such as trastuzumab (e.g., Herceptin)." (PMID 29339815, 2018). "Collectively, our in vitro data provide critical evidence suggesting the potential clinical application of ganetespib as a therapeutic strategy for ErbB2+ breast cancer." (PMID 29717218, 2018). "We, therefore, suggest a novel therapeutic approach, consisting of combined inhibition of ErbB2 and nucleolin, which has the potential to improve breast cancer treatment efficacy." (PMID 29352243, 2018). "Consistent with previous reports in other cancer models, our data provide evidence that ganetespib promotes apoptosis in ErbB2+ breast cancer cells." (PMID 29717218, 2018). "Activation of EGFR/ErbB2 signaling in tamoxifen-resistant ER+ breast cancer cells induces highly aggressive stem cell phenotype in these cells." (PMID 29455658, 2018). "We demonstrated that ERW treatment inhibited cell survival, induced apoptosis of breast cancer cells, decreased ErbB2/neu expression, and impaired pERK1/ERK2 activation, as previously reported in another cell line." (PMID 30402124, 2018). "Breast cancers over-expressing the human epidermal growth factor receptors, HER1 (EGFR/c-erbB-1) or HER2 (neu-c-erbB-2), have been associated with disease progression, survival, stage and treatment response." (PMID 29439457, 2018). "CNVs of RPL19 and RPL23 in breast cancer likely occur due to their co-amplification with ERBB2 on 17q12." (PMID 29530001, 2018). "Herceptin binds to Erbb-2 and is used widely as therapeutics in the clinics to treat HER2 positive breast cancers and gastric cancers." (PMID 30072783, 2018). "Some immunohistochemical marker of EMPD are also positive in specific type of breast cancer such as human epidermal growth factor receptor 2 (Her2/erbB2), carcinoembryonic antigen (CEA), cytokeratin 7 (CK7) and gross cystic disease fluid protein 15 (GCDFP15)." (PMID 30458743, 2018). "Overexpression of the tumor suppressor miR-34a has also been reported to suppress ErbB2 expression and breast cancer cell growth and invasion." (PMID 30214383, 2018). "The effect of the nucleolin-specific inhibitor GroA (AS1411) on ErbB2-positive breast cancer was tested in vivo, in a mouse xenograft model for breast cancer; as well as in vitro, alone and in combination with the ErbB2 kinase-inhibitor tyrphostin AG-825." (PMID 29352243, 2018). "In order to identify abnormalities and possible therapeutic targets in mature cancer arteries, we here characterize the structure and function of cancer feed arteries and corresponding control arteries from female FVB/N mice with ErbB2-induced breast cancer." (PMID 29566737, 2018). "Growth in approximately 70% of breast cancers depends on estrogen receptor (ER) expression and its related signal transduction pathway, while growth in approximately 20% of breast cancers depends on the HER2/ERBB2 status." (PMID 30647855, 2018). "Human epidermal growth factor receptor HER3 (ErbB3), a cell membrane-associated protein encoded by the ERBB3 gene, is a promising target for cancer therapy, especially in HER2-positive (carrying ERBB2/HER2 gene amplification) breast carcinoma." (PMID 30367623, 2018). "An inverse correlation between NRDP1 and HER3 expression in situ has been demonstrated in breast tumours derived from ERBB2 transgenic mice and in human breast carcinomas." (PMID 30367623, 2018). "Testing human epidermal growth factor receptor 2 gene amplification (HER2; ERBB2) is important in breast cancer (BC) and other cancers." (PMID 29564742, 2018).
breast cancer (continued). "Of note, it is known that detachment of non-malignant breast epithelial cells triggers lysosmal degradation of an ErbB2 signalling partner EGFR and that ErbB2-induced Mek activation prevents this degradation in detached breast cancer cells." (PMID 29285258, 2017). "EGFR and ErbB2 receive particular attention in the context of breast cancer etiology and therapy because of their frequent overexpression and hyperactivation in breast carcinomas." (PMID 29156633, 2017). "The rationale for using these datasets for our experiments was that—to the best of our knowledge—these are only datasets available for responsive and resistant lapatinib-treated ERBB2-positive breast cancer cell-lines." (PMID 28288164, 2017). "In BOLERO‐3, addition of everolimus to trastuzumab plus vinorelbine significantly prolongs progression‐free survival compared with placebo in patients with trastuzumab‐resistant and taxane‐pretreated, ErbB2‐positive, advanced breast cancer." (PMID 28781955, 2017). "A previous study in an ErbB2-positive breast cancer cell line BT-474 revealed that knockdown of NRF2 inhibited HER-2 expression." (PMID 28260828, 2017). "Previously, we showed that the pathway expression landscape of breast cancers with ERBB2 amplifications is largely driven by gene CNVs." (PMID 29069713, 2017). "In particular, numerous reports have shown that metformin selectively inhibits CSCs in erbB-2+ breast cancer models." (PMID 28061785, 2017). "In this study, we showed that phenformin stimulates cytotoxic and cytostatic effects in ErbB2-overexpressing breast cancer cells, which corroborates previous reports in other breast cancer cell lines." (PMID 28947975, 2017). "Given the clinical use of lapatinib as a major therapeutic agent for ErbB2+ breast cancers, lapatinib resistance has emerged as a significant clinical challenge." (PMID 28938602, 2017). "When mouse mammary-tumor derived cells that overexpress erbB2 are redirected, the auto-phosphorylation of the erbB2 tyrosine kinase is attenuated while total expression of erbB2 is not impacted." (PMID 28594912, 2017). "Consistent with the report, we found that miR-1296-5p suppressed ERBB2 expression and mTORC1 signaling, subsequently inhibited the proliferation of ERBB2-positive breast cancer cells." (PMID 29089858, 2017). "The transduced T-cells were activated and exhibited significant cytotoxicity on ERBB2 expressing breast cancer cell line." (PMID 28885562, 2017). "Several monoclonal antibodies and small molecule inhibitors have been used successfully to demonstrate the importance of ErbB2 in breast cancer pathogenesis." (PMID 29089571, 2017). "Our results in both human and mouse ErbB2-expressing breast cancer cells reveal that LPP co-localizes with Tks5 and actin at sites of matrix degradation, revealing that a population of cellular LPP is localized to invadopodia." (PMID 28436416, 2017). "Due to the limited number of studies on the anti-cancer efficacy of buformin, the effects on specific, refractory breast cancer subtypes, like erbB-2-positive breast cancer, remains to be explored." (PMID 28193239, 2017). "In this study, we evaluated the relationship between ERRF expression and the sensitivity of breast cancer cells to lapatinib in the context of ERBB2 signaling." (PMID 28415602, 2017). "These pathways include Hif-1, AMPK, TNF and calcium signaling, which were reported to be involved in lapatinib-resistance in ErbB2-positive breast cancer cell-lines." (PMID 28288164, 2017). "Drug name (Alternative name): Trastuzumab (Herceptin)Type of drug: Monoclonal antibodyMechanism(s) of Action: Trastuzumab binds to the HER2 (or c-erbB2) proto-oncogeneGenerally used for: Treatment of HER2+ metastatic (spread) breast cancer." (PMID 29254284, 2017).
breast cancer (continued). "To uncover the molecular basis for resistance of ErbB2-positive breast cancer to p110α-specific inhibition, we used an ErbB2 mouse model mimicking p110α inhibition in the goal of understanding tumor therapy escape over time." (PMID 28783168, 2017). "Both in vitro and in vivo studies indicate that alcohol significantly increased the phosphorylation of ErbB2 in breast cancer cells and mammary epithelial cells expressing high levels of ErbB2, but has little effect on cells with low levels of ErbB2." (PMID 29156633, 2017). "We performed siRNA knockdown of ErbB2 in SKBR3 human breast cancer cells to validate specific binding of KSP* to ErbB2." (PMID 29089571, 2017). "Between 20% to 30% of breast cancers over-express the human epidermal growth factor receptor 2 (HER2)/avian erythroblastosis oncogene B2 (ERBB2) protein on their cell surface, and over-expression of HER2 is strongly linked to worse clinical prognosis." (PMID 29156708, 2017). "Previous studies reported that ERBB2 induction of the invasion and migration of breast cancer cells required activation of the small GTPases and mTOR signaling." (PMID 29089858, 2017). "Overexpression of ErbB2 is found in 25% to 30% of human breast cancers and about 4% to 50% of human gastric cancers according to different examination methods and criteria." (PMID 28514745, 2017). "We demonstrate feasibility for this integrated imaging methodology to be used as an adjunct in breast cancer surgery for real-time detection of ErbB2 positive cancer cells in lymph nodes and to rapidly assess tumor margins." (PMID 29089571, 2017). "All together these results suggest that ERBB2 is a gene positively correlated with IA ancestry in Luminal breast cancer." (PMID 28832682, 2017). "For example, it was found that a therapeutic HSP90 inhibitor or an inhibitor of phosphatidylcholine-specific phospholipase C trigger lysosomal ErbB2 degradation in breast cancer cells." (PMID 29285258, 2017). "There is an imperious need to develop new and efficient targets for therapeutic intervention of ERBB2-positive breast cancers." (PMID 29089858, 2017). "Further support of this was found when applying a module score for the ERBB2 pathway from breast cancer to our data (P = 0.2896, two sided t-test, 17/28 genes present), which did not provide evidence for ERBB2 mediated activity in OCCC." (PMID 28611940, 2017). "To this end, using the well-established MMTV-erbB-2 mouse model in our current study, we found that buformin inhibits cell proliferation, cell cycle, and CSC self-renewal properties in erbB-2-overexpressing breast cancer cells." (PMID 28193239, 2017). "Our study investigated the role of CIP2A in the anti-cancer efficacy of lapatinib in ErbB2-overexpressing breast cancer cells." (PMID 28938602, 2017). "Overall, our data provides important information that can help to improve treatment options for ErbB2-positive breast cancer patients." (PMID 27791982, 2017). "Overexpression of the NRG-1 receptor subunit ErbB2 is an important driver in certain neoplasms dependent on ErbB3 and ErbB2 (i.e. HER2+ breast cancer)." (PMID 28185035, 2017). "In the primary and secondary tumorsphere formation assay, which measures the self-renewal capacity of the cells, AZD4547 inhibited both primary and secondary tumorsphere formation in a dose-dependent manner in the ErbB2-overexpressing breast cancer cell lines." (PMID 28900173, 2017). "Our cellular model emphasizes the consequences of alcohol exposure on potentially cancer-initiating DNA damage in another breast cancer subtype, ER+/ErbB2-." (PMID 28369097, 2017). "Peptidyl arginine deiminase 2 (PADI2) was first reported as an important biomarker for HER2/ERBB2+ breast cancers." (PMID 29050308, 2017). "We herein describe the role of the transcriptional repressor Blimp1 in p130Cas/ErbB2 breast cancer invasion in in vitro and in vivo models for the first time." (PMID 28442738, 2017).
breast cancer (continued). "ErbB2 is a member of the ErbB family of tyrosine kinase receptors that plays a major role in breast cancer progression." (PMID 28306722, 2017). "Mechanisms by which ErbB2 promotes three-dimensional growth of breast cancer cells are understood in part." (PMID 29285258, 2017). "MiR-221 enhances the resistance against trastuzumab and the metastasis of ERBB2-positive breast cancer by targeting PTEN." (PMID 28160563, 2017). "Nevertheless, our protein analyses in the ErbB2-overexpressing breast cancer cells indicate a close correlation between CIP2A downregulation and RTK signaling inhibition." (PMID 28938602, 2017). "Based on the PAM50 gene signature, five subtypes have been defined: Basal-like (Basal), ERBB2-overexpressing (Her2), luminal A (LumA), luminal B (LumB), and normal-breast-like breast cancer." (PMID 28695110, 2017). "We demonstrated that the drivers showed significant attributes of cancer genes, and significantly overlapped with known cancer genes, including MYC, CCND1 and ERBB2 in breast cancer, and the lncRNA PVT1 in multiple cancer types." (PMID 28719033, 2017). "In breast cancer, the ERBB2 oncogene activates signaling pathways that deregulate the essential protein processes and make cancer cells resistant to chemotherapeutic drugs of cancer cells." (PMID 28871116, 2017). "The ERBB2-positive subtype of breast cancer is characterized by gene amplification or protein overexpression of ERBB2, a member of the human epidermal growth factor receptor family." (PMID 28415602, 2017). "Here we report that ERRF also plays an important role in the response of ERBB2-positive breast cancer cells to lapatinib, a dual tyrosine kinase inhibitor that interrupts the ERBB2 and EGFR pathway." (PMID 28415602, 2017). "ErbB2 is an RTK that is found to be amplified and overexpressed in 20-30% of breast cancers, 40% of which have an activating mutation in p110α." (PMID 28783168, 2017). "Breast cancer subtypes can be categorized based on hormonal receptor (i.e. estrogen and progesterone receptors) and ErbB2/Her2 statuses." (PMID 28900173, 2017). "ERBB2 gene is up-regulated in breast cancers with highly suspicious calcifications compared to those with low-to-intermediate suspicious calcifications or those without suspicious calcifications." (PMID 28900139, 2017). "Taken together, TINCR promotes tumourigenesis partly via TINCR-MiR-125b-ERBB2 axis and its negative regulation of apoptosis pathway in breast cancer." (PMID 28738804, 2017). "For instance, cancer preventatives, like tamoxifen for estrogen receptor-positive (ER+) breast cancers, have shown clinical efficacy; yet, the prevention of ER- breast cancers, including the erbB-2-overexpressing subtype, remains elusive." (PMID 28193239, 2017). "Recently, using a mouse model for ErbB2 mammary tumours, galectin-7 expression was reported to accelerate tumour progression and the formation of tumour nodules in ErbB2-positive tumours." (PMID 29257082, 2017). "AZD4547 (1–5 μM) demonstrated potent anti-proliferative effects, inhibition of stemness, and suppression of FGFR/RTK signaling in ErbB2-overexpressing human breast cancer cells." (PMID 28900173, 2017). "As such, data from our lab have previously reported that metformin can significantly inhibit growth of syngeneic erbB-2-overexpressing mammary tumors from MMTV-erbB-2 transgenic mice inoculated with 78617 cells." (PMID 28193239, 2017). "In particular, p140Cap was described as an oncosuppressor acting as a negative regulator of cell motility and invasion, and ERBB2-mediated breast cancer progression." (PMID 28947957, 2017). "Using our in vitro system of cancer cell redirection, we investigated the genetic profiles of erbB2-overexpressing mammary tumor-derived cells as they undergo the redirection phenomenon." (PMID 28594912, 2017).